INS (insulin)
Diseases named in the same sentence as INS in open-access papers (continued):
Sharing a sentence is not in itself a finding about the gene and the disease.
abscess (19 papers, 2014 to 2026). An inflammatory process characterized by the accumulation of pus within a newly formed tissue cavity which is the result of a bacterial, fungal, or parasitic infection or the presence of a foreign body. "In contrast, the use of an insulin pen was negatively associated with abscesses (aPR = 0.13; 95% CI: 0.04-0.48, p = 0.002)." (PMID 41628120, 2026). "Nevertheless, existing literature indicates that individuals utilizing insulin are susceptible to developing abscesses and scar formation at injection sites." (PMID 41628120, 2026). "The injection site abscesses can be caused by injecting contaminated insulin stored in a water container." (PMID 35443846, 2022). "The use of insulin pens may help reduce the risk of abscesses." (PMID 41628120, 2026). "A validated case report form (CRF) was employed to gather socio-demographic characteristics and clinical data pertinent to the formation of abscesses and scars following insulin therapy." (PMID 41628120, 2026). "The patient was treated with linezolid and levofloxacin, insulin therapy, and nutritional support, and the chest wall abscess was incised and drained." (PMID 41377361, 2025). "The findings suggested a probable abscess, for which the patient was administered insulin therapy to restore glycemic control during hospitalization (short-acting insulin on sliding scale), and she underwent incision and drainage under general anesthesia." (PMID 40951149, 2025). "As a response to the daily T1D stress, the pain of injection, abscess, and insulin misconceptions, most warriors at several points in their life disengaged or avoided continuous T1D management." (PMID 37653475, 2023). "During the observation period, 6 diabetic marmosets that showed severe clinical signs such as marked weight loss (>20%), hyposthenia, dehydration, anorexia and cutaneous abscess were administered exogenous human insulin to manage their condition." (PMID 31601983, 2019). "Injection site complications include injection site infection and abscesses, injection site skin scarification (insulin tattoos), and lipohypertrophy." (PMID 29508275, 2018). "Another common challenge mentioned by many participants was the injection site pain and abscess resulting from the daily insulin injections." (PMID 28045992, 2017). "Under ultrasound guidance, pus was aspirated from the abscess and the patient was started on broad-spectrum intravenous antibiotics, insulin and low-molecular-weight heparin." (PMID 30460003, 2016). "Following drainage of the abscess and treatment with intravenous antibiotics, the abscess cavity resolved, the patient defervesced, and his insulin resistance gradually improved." (PMID 23949897, 2014). "In addition to local allergic reactions, abscess formation, scarring, lipoatrophy/dystrophy, and lipohypertrophy, LIDA broadens the differential diagnostic spectrum of local insulin injection complications." (PMID 37510159, 2023). "These should be used with caution as they may result in contamination of insulin and subsequent injection abscesses." (PMID 29508275, 2018). "Similarly, insulin in use should never be kept immersed underwater as it carries a high risk of contamination, leading to loss of potency and the likelihood of causing injection abscesses." (PMID 34136581, 2021).
alcoholic liver diseases (19 papers, 2010 to 2025). A disorder caused by damage to the liver parenchyma due to alcohol consumption. "Alcoholic liver disease (ALD) is associated with impairments in hepatic insulin and insulin-like growth factor (IGF) signaling through cell growth, survival, and metabolic pathways." (PMID 27525191, 2016). "In contrast, VEH exposure enriched pathways such as ferroptosis, insulin signaling, arginine biosynthesis, alcoholic liver disease, and NAFLD." (PMID 41282184, 2025). "The possible targets of differentially expressed miRNAs have central roles in insulin secretion, lipid metabolism, glucose metabolism, and inflammation, which are the main process involved in the occurrence and development of alcoholic liver disease." (PMID 32508647, 2020). "One of the key events during the development of alcoholic liver disease (ALD) is that alcohol inhibits the insulin signaling pathway in liver and leads to disorders of glucose and lipid metabolism." (PMID 31555134, 2019).
Blindness (19 papers, 2010 to 2024). Blindness is the condition of lacking visual perception defined as a profound reduction in visual perception. "Patients valued being encouraged to express their true beliefs around medications, such as insulin causing blindness." (PMID 37254880, 2023). "For example, estimations indicate a 23.7% relative reduction for amputation and 11.3% relative reduction for blindness in the simple insulin infusion group compared to the MDI group." (PMID 32685574, 2018).
cyst (18 papers, 2013 to 2026). A sac-like closed membranous structure that may be empty or contain fluid or amorphous material. "The activation of mTORC1 by insulin and nutrient signals also enhances the expression of glycolytic and lipogenic genes, thereby supporting cyst expansion." (PMID 40722668, 2025). "Elevated insulin levels and nutrient availability further enhance hormonal metabolic processes, promoting cyst growth." (PMID 40722668, 2025). "The proposed molecular mechanism behind cyst progression is that increased insulin resistance stimulates the mTOR pathway, which is dysregulated in PKD." (PMID 41305569, 2025). "Excess androgens induce the excessive release of LH by the pituitary gland and promote the ovarian production of androgens, weight gain, anovulation, and cyst formation in the ovaries, either directly or through a mechanism of action involving insulin." (PMID 38283184, 2024). "High levels of insulin and IGF-1 also amplify the effect of LH on granulosa cells, causing premature differentiation, follicle growth arrest, anovulation, and cyst formation." (PMID 38283184, 2024). "For patients receiving tolvaptan, a vasopressin V2 receptor antagonist that slows cyst growth, plant-based diets may offer complementary benefits by improving insulin sensitivity, reducing oxidative stress, and mitigating dietary acid load." (PMID 41305569, 2025). "Methylprednisolone treatment prior to surgery may have increased the cyst fluid level of insulin, as suggested by the correlation between length of treatment and cyst fluid insulin concentration." (PMID 35659255, 2022). "Given that insulin/insulin-like growth factor signaling functions in the ovary to control germline cyst survival and progression through vitellogenesis, adipocyte-derived CCHamides and egr might control the survival of early and late germlines by controlling ILP secretion from brain IPCs." (PMID 40305230, 2025). "Similarly, reduced serum insulin concentrations during early postpartum may contribute to ovarian dysfunction, including cyst formation." (PMID 40725447, 2025). "The action of Insulin on ovarian also might cause hyper-androgenic inducing, lack of ovulation and cyst creation in PCOS patients." (PMID 30524997, 2018). "There is evidence that NEB, low insulin and IGF-1, and altered metabolic hormones contribute to anovulation and cyst formation." (PMID 40725447, 2025). "Our data indicated that the average insulin and IGF-1 concentrations in the follicular fluids of follicular cyst follicles were significantly lower than in control follicles." (PMID 37958056, 2023). "The concentration of some hormones in cyst fluid was lower than (IGF-1, insulin) or similar to (growth hormone, testosterone, triiodothyronine) the serum concentration." (PMID 35659255, 2022). "In cyst fluid from 25 patients with cystic glioblastomas (nine women and 16 men), several hormones were present: IGF-1, insulin, erythropoietin, growth hormone, testosterone, estradiol, and free triiodothyronine." (PMID 35659255, 2022). "A recent study showed that the input of the insulin pathway on GSC proliferation, cyst growth, and vitellogenesis is entirely mediated by phosphatidyl-inositol-3-kinase in Drosophila." (PMID 23450845, 2013). "Cyst fluid levels of IGF-1 and growth hormone correlated with cyst fluid levels of serum proteins, suggesting the importance of BBB dysfunction, whereas levels of erythropoietin and insulin did not correlate with serum protein levels in cyst fluid." (PMID 35659255, 2022). "We did not observe a different effect of insulin as previously reported, perhaps because the racemose larvae of T. solium and the cyst of T. crassiceps proliferate from the bladder wall in a similar manner." (PMID 33750965, 2021).
cyst (continued). "β-cells induced from iPSCs of a diabetic patient frequently produced spheroids with a hollow cyst that did not differentiate into insulin-producing cells, suggesting that a hollow cyst can be an indicator of the failure in β-cell differentiation from iPSCs." (PMID 34252142, 2021). "Therefore, reduced insulin and IGF-1 levels may have an influence on the follicular responsiveness to LH stimulation and then result in ovulation failure and further cyst formation." (PMID 37958056, 2023). "Insulin and insulin receptors in ovaries have several important impacts on ovaries; androgen secretion stimulation, steroidogenic response creation of ovaries to LH, FSH hormones and process harness of apoptosis in ovarian follicles which leads to cyst formation." (PMID 30524997, 2018). "In addition, insulin increases the bioavailability of insulin-like growth factor 1 (IGF-1) and both insulin and IGF-1 were reported to amplify the effects of LH on granulosa cells, leading to their premature differentiation which results in follicular growth arrest, anovulation and cyst formation." (PMID 32917200, 2020).
cystic fibrosis-related diabetes (18 papers, 2006 to 2025). Cystic fibrosis-related diabetes is a form of diabetes that occurs frequently in individuals with cystic fibrosis. "Cystic fibrosis-related diabetes is associated with decreased first phase insulin release (depolarization dependent), while second phase insulin (depolarization independent) remains intact." (PMID 29515516, 2018). "The primary objective of this trial is to compare the glycaemic control of oral therapy with Repaglinide with insulin injections in patients with cystic fibrosis related diabetes after 2 years of treatment." (PMID 24620855, 2014). "Insulin is the recommend therapeutic agent of choice for the management of Cystic Fibrosis Related Diabetes (CFRD), despite only sub-optimal reductions in glycemic control and increased morbidity and mortality reported by centers using this agent." (PMID 16790062, 2006). "In summary, we believe that CFTR affects the pancreas functionality and the insulin-responsive tissues; both contribute to cystic fibrosis-related diabetes (CFRD)." (PMID 33659254, 2021). "Pregnancy in women with cystic fibrosis-related diabetes (CFRD) is rare and requires intensive monitoring and individualized treatment due to the pathophysiologic parameters of the disease in relation to insulin therapy and special nutritional needs." (PMID 32742862, 2020). "The evolving understanding of cystic fibrosis-related diabetes (CFRD) underscores the importance of unraveling the intricate interplay between oxidative stress, inflammation, and insulin secretion in its pathogenesis." (PMID 37893045, 2023). "The algorithm was applied to data from 17 subjects with normal glucose regulatory systems and 9 subjects with cystic fibrosis related diabetes (CFRD) in which glucose, insulin and c-peptide were measured in course of oral glucose tolerance tests (OGTT)." (PMID 35991187, 2022). "The ease of weight manipulation through misuse or abuse of pancreatic enzymes, glucocorticoids or insulin (in Cystic Fibrosis Related Diabetes (CFRD)) should not be overlooked." (PMID 34917482, 2021).
injury (18 papers, 2012 to 2026). Damage inflicted on the body as the direct or indirect result of an external force, with or without disruption of structural continuity. "A recent study found that intranasal insulin improves memory, increases cerebral glucose uptake, and decreases neuroinflammation and hippocampal lesion volume caused by traumatic brain injury in rats." (PMID 31354415, 2019). "Hypoglycemia-induced brain injury is a common and serious complication of intensive insulin therapy experienced by Type 1 diabetic patients." (PMID 24124562, 2013). "Traumatic brain injury initiates a dramatic systemic stress response with the release of cortisol, catecholamines, and glucagon leading to excessive hepatic gluconeogenesis and peripheral insulin resistance." (PMID 28993802, 2017). "It is physiologically plausible that the effect of insulin on brain glucose metabolism may be altered by brain injury." (PMID 22277085, 2012). "The differences in those who responded to enteral phosphorus therapy versus those who worsened could not be explained by the differences in carbohydrate, caloric, or insulin intakes, arterial pH, presence of traumatic brain injury or other clinical or laboratory parameters." (PMID 38732640, 2024).
lymphoma (18 papers, 1990 to 2023). A malignant (clonal) proliferation of B- lymphocytes or T- lymphocytes which involves the lymph nodes, bone marrow and/or extranodal sites. "Recent studies suggest that insulin treatment may be associated with an higher risk of the developing certain types cancers including lymphoma." (PMID 23734852, 2013). "It is possible the effect of fasting on AE associated with vincristine, and glucose, insulin and IGF‐1 concentrations vary with patient stage and immunophenotype of lymphoma." (PMID 33448618, 2021). "To overcome this issue, we transiently transfected the LB17 lymphoma cells with a minigene carrying the v5 exon and surrounding intron sequences, flanked by insulin exons (pETv5)." (PMID 18183298, 2008). "A study has been carried out in which a comparison was made between EL4 lymphoma (assumed to be an insulin-producing secreting tumour) and thymoma (an insulin-dependent tumour)." (PMID 2186773, 1990). "We tested whether the insulin sensitizer, metformin, known to have anti-cancer activity, could impact canines with drug resistant lymphoma when added to chemotherapy." (PMID 36077749, 2022). "Dogs with lymphoma may have abnormal carbohydrate metabolism, as this group has been reported to have higher insulin levels compared with controls." (PMID 33448618, 2021). "However, insulin use increased from 26% of patients at the time of lymphoma diagnosis to 35% during the year after diagnosis." (PMID 33437504, 2020). "Although the insulin sensitivity of skeletal muscle was also reduced in patients with lymphoma, the net insulin effect may counteract imbalance between glucose uptake of tumour and muscle, offering a potential means to circumvent at least some metabolic abnormalities found in cancer." (PMID 22275952, 2007). "These include stimulation of gluconeogenesis in hepatocytes, induction of insulin secretion in islet β‐cells exposed to fatty acids, and survival of FAO‐dependent lymphoma subtypes." (PMID 36917141, 2023). "Next, to validate downregulation of the PI3K/AKT/mTOR pathway in Eμ-Myc lymphomas upon PRDM15 depletion, we starved WT and KO cells overnight and subsequently stimulated them with insulin and IGF1." (PMID 32665551, 2020).
Neonatal hypoglycemia (18 papers, 2014 to 2025). "Risk for any neonatal hypoglycemia still remained significantly higher with glyburide compared to insulin [RR, 2.29; 95%CI, 1.49 to 3.54; p = 0.0002], with I2 decreased from 41% to 13%." (PMID 28771572, 2017). "All trials included in this meta-analysis reported the incidence of neonatal hypoglycemia and the results indicated a higher risk of any neonatal hypoglycemia after maternal treatment with glyburide compared to treatment with insulin (p = 0.002)." (PMID 28771572, 2017). "Our meta-analysis of glyburide and insulin revealed a significant increase in the risk of macrosomia and neonatal hypoglycemia in the glyburide group." (PMID 25302493, 2014). "In another study, neonatal hypoglycemia was observed in more cases with glyburide than insulin and acarbose." (PMID 33403188, 2020). "In the pairwise meta-analysis, we observed that glyburide had higher incidence of neonatal hypoglycemia compared with insulin (RR, 1.76; 95% CI, 1.32 to 2.36; P < 0.001)." (PMID 31781670, 2019). "Neonatal hypoglycemia was reported as an outcome between glyburide and insulin by 12 studies which included 2406 GDM patients." (PMID 31781670, 2019). "In the pairwise meta-analysis, metformin had lower incidence of neonatal hypoglycemia than insulin (OR, 0.636; 95% CI, 0.486–0.832), and insulin was lower than glyburide (OR, 0.647; 95% CI, 0.423–0.991)." (PMID 28930827, 2017). "As for the incidence of neonatal hypoglycemia, metformin had lower incidence than insulin and glyburide (OR, 0.6331 and 0.3898), and insulin was lower than glyburide (OR, 0.6236)." (PMID 28930827, 2017). "Lower storage of glycogen, increased free insulin, absence of substrate source for gluconeogenesis, and increased insulin sensitivity in these at-risk infants are related to neonatal hypoglycemia." (PMID 38129821, 2023). "Data, such as MODY type, the gestational age at delivery, mode of delivery, insulin administration, mutational status of the fetus, fetal birthweight (FBW), occurrence of small-/large-for-gestational age fetus, shoulder dystocia, and neonatal hypoglycemia, were extracted and evaluated." (PMID 40649834, 2025).
Ovarian Hyperandrogenism (18 papers, 2011 to 2025). Increased production of androgens by the ovaries. "Women with PCOS have abnormalities of insulin secretion and action, and underlying IR has been proposed to be fundamental to the development of ovarian hyperandrogenism." (PMID 21899727, 2011). "It is speculated that insulin’s stimulating effect on ovarian androgen synthesis may lead to ovarian hyperandrogenism, which in turn may reduce the risk of BC in premenopausal women." (PMID 37790752, 2023). "This diminishes VLDL secretion from the liver and indirectly alleviates ovarian hyperandrogenism by reducing systemic insulin levels." (PMID 41010046, 2025). "Evidence suggests that ovarian hyperandrogenism is a result of insulin action on the ovaries, and because of that, it is mediated by IGF-1R." (PMID 33910166, 2021). "Insulin excess stimulates androgen production by theca cells and elevates serum free testosterone levels, thereby perpetuating ovarian hyperandrogenism." (PMID 24693338, 2014). "Girls born SGA with catch-up growth present with lower insulin sensitivity, and there are data showing an increased incidence of adrenal and ovarian hyperandrogenism clinically evident as precocious pubarche." (PMID 21771322, 2011). "From a medicinal standpoint, engineered hepatocyte-derived EVs harbouring anti-miR-122 antagomirs have the ability to modulate hepatic lipid metabolism (via SREBP1c suppression), reduce systemic insulin levels, and indirectly alleviate ovarian hyperandrogenism." (PMID 41010046, 2025). "It is hypothesized that exogenous insulin therapy in T1DM, which bypasses hepatic first-pass metabolism and leads to elevated systemic insulin levels, may contribute to ovarian hyperandrogenism by stimulating theca cells androgen direct or indirect release." (PMID 40427455, 2025). "PCOS induction led to ovarian hyperandrogenism and significantly increased basal insulin secretion." (PMID 38678269, 2024). "The effects of excessive insulin action on the ovary, which appear to be independent of the insulin receptor (INSR), are suggested to drive ovarian hyperandrogenism in common PCOS." (PMID 33901270, 2021).